IL33 (interleukin 33)
Diseases named in the same sentence as IL33 in open-access papers (continued):
Sharing a sentence is not in itself a finding about the gene and the disease.
tumor (continued). "Considering a highly fibrotic tumor such as pancreatic ductal carcinoma, the authors show that IL-33 was mainly upregulated by cancer-associated fibroblasts (CAFs) and pericytes, driving M2 polarization mediated by the ST2 receptor." (PMID 39086395, 2024). "In line, blocking tumor-associated macrophages which decreases TNFα and elevates IL33 resulted in increased DC activity and infiltration of cytotoxic T cells, with anti-tumor activity." (PMID 38942797, 2024). "In CT26 colon cancer cell engraftment models, IL-33 treatment demonstrated a notable reduction in tumor growth, a phenomenon intricately linked to eosinophils." (PMID 38881897, 2024). "The ST2/IL-33 axis is also essential for the recruitment and activation of T-regs, tumor-associated macrophages (TAMs), group 2 innate lymphoid cells (ILC2s), and mast cells." (PMID 39609700, 2024). "IL-33 was also reported to directly induce the proliferation or migration of tumor-associated cells." (PMID 37246159, 2023). "In conclusion, despite some limitations, the results of this study suggest that high IL-33 expression was positively associated with higher tumor stage, lymphatic invasion, and other pathological characteristics." (PMID 37507682, 2023). "Mast cells are activated by tumor-derived IL-33 through the recruitment of tumor-associated macrophages and their support of vascular networks to maintain tumor growth." (PMID 37153553, 2023). "Il-33 plays an alarming signal molecule role which is engaged in the tumor-associated inflammation process." (PMID 36836154, 2023). "In gastric cancer, IL-33-mediated mast cell activation promotes tumor growth by inducing tumor-associated macrophage mobilization." (PMID 37246159, 2023). "In the current study, we clearly elucidated the distinct mechanisms underlying the dual role of IL-33 in tumor development." (PMID 37056569, 2023). "These elevated IL-33 levels seem to be linked to a shortened period of tumor-free survival before a recurrence, indicating the potential detrimental impact of IL-33 on patient prognosis." (PMID 37762328, 2023). "Systemic accumulation of eosinophils in tumor cells mediated by IL-33 is associated with improved progression-free and overall survival in triple-negative breast cancer (TNBC)." (PMID 37296602, 2023). "In the ApcMin/+ mouse model of intestinal tumorigenesis, genetic and antibody loss of responsiveness to IL-33 reduces tumor number and size by inhibition of proliferation, induction of apoptosis, and suppression of angiogenesis in adenomatous polyps." (PMID 37296602, 2023). "IL-33 activates tumor-associated macrophages and dendritic cells by binding to its receptor, ST2, triggering the release of abundant Th2 cytokines, including IL-10, IL-4, and IL-13, which inhibit immune cell responses, hampering tumor clearance and control." (PMID 37686309, 2023). "At the serum expression level, the overall analysis showed that the expression of IL-33 increased the risk of cancer, and the serum level of IL-33 was positively correlated with tumor stage and vascular invasion." (PMID 37507682, 2023). "The analysis of the correlation between VISTA and other markers of OSCC showed that higher levels of VISTA H-score were associated with higher levels of IL-33 expression on both tumor cells and lymphocytes and PD-L1 assessed on tumor cells." (PMID 36836154, 2023). "In the tumor stroma, pericytes produce IL-33, which recruits and activates tumor-associated macrophages, ultimately promoting metastasis." (PMID 36967785, 2023). "As expected, in vivo experiment indicated that anti-fungal treatment or IL-33 deficiency decreased the infiltrating level of Th2 cells and ILC2s, leading to tumor regression and increased survival in PDAC-bearing mice." (PMID 37868956, 2023). "IL-33 deficiency or blockade led to reduced tumour Il4, Il6 and Il13 expression, and correlated with reduced tumour mast cells." (PMID 36263033, 2022).
tumor (continued). "IL-33 treatment reduced tumour burden and is associated with an increase in eosinophil gene expression in tumours." (PMID 36263033, 2022). "Loss of IL-33 markedly reduced tumorigenesis in gp130F/F antra, as shown by a significant decrease in macroscopic antral tumour area (52.23 ± 5.00 vs. 30.99 ± 4.94 mm2, P < 0.05)." (PMID 35677533, 2022). "IL-25 promotes tumorigenesis through activating ILC2s which sustain tumour M-MDSCs to suppress T cell and IFNγ-mediated anti-tumour immunity.IL-33 deficiency is associated with a reduction in tumour Tregs and mast cells." (PMID 36263033, 2022). "In the TME, pericytes are also the main source of IL33, and thus responsible for recruiting tumor-associated macrophages (TAMs) via the IL33-ST2 signaling pathways." (PMID 36428576, 2022). "Conversely, loss of nuclear IL-33 resulted in significantly smaller IL-33-associated tumour burden and increased overall survival." (PMID 36555253, 2022). "IL-33 has a dual role in established cancer and has been associated with both anti-tumor and pro-tumor immune responses." (PMID 36032129, 2022). "Our findings cannot elucidate the mechanism underlying the increase or decrease in the levels of IL-33 and other cytokines in the tumor microenvironment." (PMID 35565267, 2022). "In an orthotopic caecal implant model of CRC using MC38 cells, overexpression of IL-33 in tumour cells led to increased liver metastasis that was associated with an increased recruitment of CD11b+Gr1+ MDSCs and tumour angiogenesis." (PMID 36263033, 2022). "Both subfamilies of IL-1 accelerate GBM relapse, however, blocking IL-1β and IL-33 can reduce tumor progression-associated compensation mechanisms including the Warburg effect." (PMID 35572545, 2022). "Genetic overexpression of IL-33 in tumour epithelial cells is associated with an increase in colonic alternative activated macrophages and ST2+ Tregs." (PMID 36263033, 2022). "IL-33 is produced from epithelial cells, endothelial cells, and tumor-associated fibroblasts within the TME." (PMID 35805039, 2022). "IL-33 is implicated in tumor-associated inflammation, such as ulcerative colitis, gastritis and GERD." (PMID 36110250, 2022). "Correspondingly, amphotericin B treatment or IL-33 deficiency significantly reduced tumor burden, improved survival, and decreased tumor-infiltrating ILC2 cells and Th2 cells." (PMID 35910636, 2022). "In gastric cancer, a linear signaling axis activated by tumor epithelial-derived IL-33 was found to activate mast cells and promote tumor-associated macrophage (TAM) accumulation." (PMID 36159780, 2022). "Overexpression of IL-33 in tumour cells is associated with increased recruitment of tumour MDSCs and enhanced angiogenesis." (PMID 36263033, 2022). "Conversely, in another study genetic deficiency of IL-33 significantly enhanced tumour burden in AOM/DSS-treated mice." (PMID 36263033, 2022). "Epithelial cell-expressed IL33 is associated with increased tumor immunogenicity by driving CD8+ T cell and dendritic cell type 1 (DC1)-dependent antitumor immunity." (PMID 33553191, 2021). "Although there was evidence of reduced apoptosis, tumor weight, tumor volume, and tumor growth were all reduced in IL-33-deficient mice, a beneficial outcome for cancer prognosis." (PMID 33805488, 2021). "It has been reported that IL-33 is associated with tumorigenesis, metastasis, and proliferation of tumor cells." (PMID 33946554, 2021). "Here, we found elevated levels of IL‐33 in the tumour tissue samples, which were also associated with the upregulated density of CD206+ M2‐like macrophages (R2 = .65)." (PMID 33305406, 2021). "Accumulating evidence reveals that the IL-33/ST2 signaling axis is linked closely to tumorigenesis as well as to tumor immunity." (PMID 34209038, 2021). "The authors showed that high IL-33 expression in tumor cells was associated with local and nodal recurrence." (PMID 34572318, 2021).
tumor (continued). "The metastasis-promoting effect of IL-33 expressed in CAFs was associated with the switch of tumor-associated macrophages (TAMs) from anti-tumorigenic M1 to pro-tumorigenic M2 phenotype." (PMID 34209038, 2021). "We first analyzed the mRNA expression levels of damage-associated molecules (HMGB1, HSP60, HSP70, S100A8, IL-1A, IL-33) in 11 canine tumor cell lines." (PMID 33875721, 2021). "In the two metastasis sub-cohorts, IL-33 is associated with better prognosis and more active immune responses in the tumor." (PMID 33621202, 2021). "In line with this, the underlying molecular mechanisms and the potential effect of IL-33 on tumor development remain to be evaluated." (PMID 32003751, 2020). "Direct stimulation of NK, CD8+ and CD4+ T cells by IL-33 has been reported to promote Th1-associated anti-tumor responses in several tumor models." (PMID 33329534, 2020). "High levels of IL-33 in the presence of pathogen-associated molecular pattern–induced IL-12 promote type I anti-tumour immune response." (PMID 33308251, 2020). "Recent studies have revealed that IL-33 plays a functional role in tumor development, with high levels of serum IL-33 associated with poor prognosis and chemotherapy resistance in various cancers." (PMID 31659258, 2020). "Previous studies have demonstrated that IL-33 promotes cancer metastasis through recruitment of tumor-associated macrophages (TAMs)." (PMID 31659258, 2020). "A high tumor expression of IL33 was then associated with advanced disease and an adverse prognosis; additional experimental studies showed that IL33 enhanced cancer cell growth and induced chemoresistance." (PMID 32707675, 2020). "In an HPV-associated mouse tumor model, IL-33 promoted IFN-γ and TNF-α production by antigen-specific CD4+ T cells." (PMID 33329534, 2020). "The mechanism proposed to be responsible for the enhanced tumor growth involves the ability of IL-33 to cause an increase in the number of infiltrating immunosuppressive immune cells and innate lymphoid cells to the tumors, drive the tumorigenic process." (PMID 31231372, 2019). "Accumulating evidences have implicated that IL-33 plays a critical role in tumor initiation and progression." (PMID 30691509, 2019). "This appeared to be due, in part, to modulation of the tumor microenvironment by IL-33-producing CAFs, which caused the transition of tumor-associated macrophages from an M1 (anti-tumorigenic) to an M2 (pro-tumorigenic) phenotype." (PMID 31231372, 2019). "The presence of a Transwell membrane between cells significantly abrogated tumor apoptosis caused by IL-33 EO, whereas it was irrelevant for IL-5 EO, implying that cell contact was absolutely required for IL-33 induced tumoricidal functions of eosinophils." (PMID 31717819, 2019). "Here, IL-33 EO tightly bound to tumor cells and showed emptying granules, revealed by loss of electron density, in proximity of contact region." (PMID 31717819, 2019). "IL-33 has been reported to be highly expressed in tumor tissue, in which nutrient gradients cause necrotic areas and release of bioactive IL-33." (PMID 31396219, 2019). "Our preclinical data argue strongly for a tumor promoting role of a signaling axis emanating from IL-11-induced, tumor cell-derived IL-33 and the subsequent hierarchical activation cascade of mast cells and tumor-associated macrophages." (PMID 31227713, 2019). "In HNSCC, the upregulation of LncCAF (FLJ22447) in cancer-associated fibroblasts (CAFs) upregulates cytokine IL-33, supports tumor growth and leads to a poor prognosis." (PMID 31416244, 2019). "Interleukin (IL)-33 and regulatory T cells (Tregs) in the tumor microenvironment have been separately implicated in CRC; however their contribution to intestinal carcinogenesis is still controversial." (PMID 31165767, 2019).
tumor (continued). "In the present study, we observed an association between tumor and stromal IL-33 and ST2 localization with desmoplasia in CRC patients, coupled with IL-33 increased in left-sided CRC patients with LN metastasis." (PMID 31281317, 2019). "First, the association analysis of the IL-33/ST2 distribution in tumor epithelium shows that IL-33 immunoreactivity is directly associated with a greater amount of desmoplasia, observing a similar trend with ST2 immunoreactivity." (PMID 31281317, 2019). "Some data have reported a positive association between IL-33 production in cancer cells and the best prognosis in tumor subjects, where IL-33 and ST2 concentrations were downregulated in cancer lung cells." (PMID 31652497, 2019). "Induction of tumor apoptosis by IL-33-activated eosinophils was associated with the formation of increased numbers of conjugates with target tumor cells, demonstrated by flow cytometry and CLSM analysis, and was abrogated in the absence of cell contact." (PMID 31717819, 2019). "IL-33 modulates the tumor-associated inflammatory microenvironment by activation of the NF-κB pathway and Th1 transcription factor T-bet, promoting proliferation, activation and infiltration of CD8+ T cells and NK cells." (PMID 31396219, 2019). "Although kidney expression of the pro-inflammatory cytokines CXCL1 and TNF-α increased in IL-33 deficient mice, surprisingly, tumor weight, volume, and growth were significantly decreased and the effect of cis-platin on tumors was greatly enhanced." (PMID 30205617, 2018). "The data showed that localized infiltration of IL-33+ cells within the tumor and infiltrative margins was associated with increased patient survival, with more cells localized in the near and distant stroma as compared to tumor regions." (PMID 30205617, 2018). "Most of the current studies on IL-33's multiple roles in cancers focus on tumor microenvironment, tumorigenesis and tumor-associated inflammatory responses." (PMID 30619376, 2018). "Interleukin-33 (IL-33), an “alarmin” cytokine, has been implicated in tumor associated immune responses and inflammatory diseases of the lung." (PMID 29499051, 2018). "Decrease in IFN-γ was associated with more aggressive CRC in human patients indicating that loss of IL-33 signaling impaired a potent IFN-γ mediated anti-tumor immune response." (PMID 30205617, 2018). "For instance, a replicating viral vector system used in cancer immunotherapy which delivers tumor-associated antigens to DC for efficient cytotoxic T cells priming, depends on IL-33 signaling." (PMID 30416507, 2018). "Such stromal remodeling effects of IL-33 have been shown to promote tumor cell growth and liver metastasis in IL-33-deficient mice with a metastatic murine CRC cell line." (PMID 30547011, 2018). "Some studies have demonstrated that interleukin-33 (IL-33) is an immunomodulatory cytokine that is associated with the immune regulation of tumor cells." (PMID 29736154, 2018). "After recruitment, macrophages are directly induced by IL-33 to be polarized in M2 tumor associated macrophages (TAM) in the TME." (PMID 30416507, 2018). "Several lines of evidence indicate that IL-33 amplifies the expression of M2 markers on macrophages in vitro and in vivo, thus promoting the suppressor function of tumor-associated macrophages (TAMs)." (PMID 30483263, 2018). "Later studies showed that IL-33 blockade inhibited tumor growth by abrogating the polarization of M2 tumor-associated macrophages (TAMS) and reducing accumulation of Tregs in the TME thereby shaping functional immune surveillance." (PMID 30205617, 2018). "Tumor expression of IL-33 was associated with poor survival and can potentially be targeted to treat metastatic CRC." (PMID 30205617, 2018). "Of important, blockade of IL-33 restricted tumor progression of human NSCLC xenograft in immune-deficient mice." (PMID 29568370, 2018).
tumor (continued). "We will also discuss the possible implications of diverse IL-33 mutations and isoforms in the anti-tumor activity of the cytokine and as possible clinical biomarkers." (PMID 30483263, 2018). "Our data showed that lower IL-33 protein expression in adenocarcinoma tissues was significantly associated with higher tumor grade (P = 0.0342)." (PMID 29499051, 2018). "Several studies have shown that IL-33 is associated with tumorigenesis, metastasis, and proliferation of tumor cells." (PMID 29736154, 2018). "IL-33 is a cytokine implicated in mutual modulation of not only anti-tumor immunity but tumor growth." (PMID 30619376, 2018). "Ablation of IL-33/ST2 signaling by using ST2 deficient mice significantly prevents tumor formation in the azoxymethane (AOM)/dextran sodium sulphate (DSS) model of CRC26." (PMID 28710436, 2017). "Meanwhile, IL-33 blockade abrogated polarization of M2 tumor-associated macrophages (TAMs) and reduced accumulation of regulatory T cells (Tregs) in tumor microenvironments, shaping functional immune surveillance." (PMID 28978138, 2017). "By engraftment of tumor tissues from NSCLC patients into immune-deficient mice and subsequent treatment of tumor-bearing mice with IL-33 blockers, we demonstrate that blockade of IL-33 is an efficient strategy to limit NSCLC growth." (PMID 28978138, 2017). "In IL-33R−/− mice we detected lower expression of VEGF in tumor cells, suggesting that IL-33/IL-33R signaling is associated with expression of VEGF." (PMID 26919112, 2016). "Here the authors show in mouse tumour xenograft models that PDGF-BB produced by tumour cells induces IL-33 via Sox7 in tumour pericytes, and IL-33 promotes metastasis through its effects on tumour-associated macrophages." (PMID 27150562, 2016). "Since our study indicated increased tumour metastasis linked to IL-33, we investigated further the link between IL-33-induced TAMs and tumour metastasis." (PMID 27150562, 2016). "Parallel studies in humans demonstrate that low tumour expression of IL-33 is an immune biomarker associated with recurrent prostate and kidney renal clear cell carcinomas." (PMID 27619158, 2016). "Based on the established role of IL-1Family members, including IL-1β and IL-18, in GI-related cancers, the possibility exists that IL-33 can likewise play an important role in GI-associated tumor formation." (PMID 23062310, 2012). "Overall, the interleukin profiles indicate that IL-8 and IL-33 are more closely associated with localized or intermediate stages of tumor invasion, while IL-17A demonstrates a steep decline in advanced disease, potentially reflecting immune suppression during metastatic progression." (PMID 40725273, 2025). "Furthermore, cytokines and signaling molecules such as IL-33, IL-6, GM-CSF, IL-4, and IL-10 orchestrate histone modification patterns in tumor-infiltrating MDSCs and tumor-associated macrophages (TAMs), enhancing their immunosuppressive functions." (PMID 41301911, 2025). "Hypoxia and tissue damage, common in rapidly growing tumours, promote passive IL-33 release from necrotic stromal/epithelial cells and activate stromal cancer associated fibroblasts (CAFs), which can amplify IL-33 production and secrete chemokines that recruit Tregs and MDSCs." (PMID 41284319, 2025). "Similarly, IL-33 has been implicated in tumor metastasis; elevated IL-33 levels are observed in invasive tumors where it contributes to the remodeling of the tumor microenvironment and promotes angiogenesis, thereby supporting disease progression." (PMID 40725273, 2025). "In contrast, IL-33-driven type 2 immunity is associated with tumor progression." (PMID 41087719, 2025). "Perhaps, the down-regulation of IL-33 that was linked to the low HLA expression levels in human prostate tumours is a part of the same miR-19-mediated regulatory network, which leads to failed activation of ILC2s and poor tumour outcomes." (PMID 38172434, 2024).